ENSG00000212270
Synonyms: LOC124900350
Gene: Small nucleolar RNA gene on chromosome 14 (25,806,648 to 25,806,712, reverse strand). Ensembl gene ENSG00000212270.
Gene Ontology:
Biological process: RNA processing
Cellular component: nucleolus
Homologues: Paralogues in human: SNORD37 (82% identical).